INS (insulin)
Diseases named in the same sentence as INS in open-access papers (continued):
Sharing a sentence is not in itself a finding about the gene and the disease.
metabolic syndrome (continued). "The findings of this study indicate insulin mimetic and insulin sensitizing as well as anti-inflammatory actions of EWH in adipocytes which may potentially prevent or alleviate the complications of metabolic syndrome." (PMID 28972997, 2017). "In the multiple logistic regression analyses, the full model showed that a high dioxin level was a risk factor for CKD (AOR = 1.74, 95% CI: 1.02–2.97), independent of gender, mercury level, metabolic syndrome, DM, hypertension, insulin level, uric acid level, and age." (PMID 26963719, 2016). "In Europeans with metabolic syndrome, vitamin D status may not correlate with insulin activity or secretion, and relationships between vitamin D status and IR differ among different racial groups." (PMID 27413370, 2016). "These abundances correlated positively with biomarkers for metabolic syndrome (e.g., BW, AI, AUC during GTT, fasting blood glucose level, the HOMA2-IR index, and faecal LCN-2 levels), and correlated negatively with biomarkers for insulin sensitivity (e.g., QUICKI and HOMA2-%S indices)." (PMID 27471110, 2016). "Notably, individuals who have the metabolic syndrome will be more insulin resistant than those who do not, which is in line with the original concept that was proposed by Reaven1." (PMID 27803798, 2016). "In a subsequent 6-week intervention with the same experimental design on 44 obese subjects with Metabolic Syndrome, endothelial function measured as peripheral arterial tone, significantly improved with blueberry consumption, while blood pressure and insulin sensitivity did not significantly change." (PMID 27706020, 2016). "Similarly, a weight-stable Nordic diet for 18–24 weeks did not alter insulin sensitivity and blood pressure in people with metabolic syndrome." (PMID 26742071, 2016). "Third, except for insulin use, this study did not collect information on the use of other anti-diabetic medications, or medications commonly used in the diabetic patients for the treatment of dyslipidemia and hypertension." (PMID 27906989, 2016). "Insulin dose, in this case, could be regarded as a surrogate marker of this hyperinsulinaemic environment, analogously to plasma insulin in non-diabetic individuals with the metabolic syndrome." (PMID 27011769, 2016). "Although our retrospective data set did not permit characterization of metabolic syndrome in individual patients, our findings suggest complex interactions between insulin and energy metabolism versus prostate cancer development, and prostate cancer progression." (PMID 27599544, 2016). "However, human Cushing’s patients also show increased insulin-stimulated endothelin release which is not a feature of metabolic syndrome alone." (PMID 27684374, 2016). "We fed Western diet to WT and caspase-2-deficient mice for 16 weeks, and despite similar food intake, caspase-2-deficient mice gained less weight and fat mass, were more glucose tolerant and insulin sensitive, did not develop dyslipidemia, and were protected from NAFLD." (PMID 26890135, 2016). "Significant changes seen in the lipid profiles in our study between case and control groups may confirm a possible systemic effect of EA in reversing dyslipidemia, especially by the modulation of FFA levels, which can in turn influence insulin secretion and IR in T2DM." (PMID 27136447, 2016). "Consequently, if a laboratory measurement was to be considered to be added to the metabolic syndrome criteria, our findings and other pathophysiologic arguments would favor adding insulin over HbA1c, as it was proposed in the initial WHO definitions of the metabolic syndrome." (PMID 26241903, 2015). "Impaired insulin sensitivity is a classic symptom of metabolic syndrome and the finding that both adiponectin and Akt phosphorylation increased in a depot specific manner in the WAT of SJW-treated animals provides evidence of an insulin-sensitizing effect of this botanical extract." (PMID 25136373, 2014).
metabolic syndrome (continued). "We did not see any improvement in terms of dyslipidemia or insulin sensitivity." (PMID 24586518, 2014). "On the other hand, switching to RAL did not improve dyslipidemia and insulin sensitivity." (PMID 24586518, 2014). "Emerging evidence also indicates that carotid bodies might sense insulin directly independent of its effect on glucose, linking the carotid bodies to the pathophysiological consequences of the metabolic syndrome." (PMID 25642193, 2014). "In summary, switching from d4T to RAL in patients with HALS induces a remarkable increase in limb fat mass with and improvement of molecular markers of adipocyte differentiation and mitochondrial function in SAT, without beneficial effects on dyslipidemia or insulin sensitivity." (PMID 24586518, 2014). "Thus the rats show some of the characteristics of the metabolic syndrome being obese, insulin resistant and hyperlipidaemic, but not diabetic." (PMID 25197961, 2014). "Lack of insulin may account for dyslipidemia, since insulin has an inhibitory activity on HMG-CoA reductase, a key rate-constraining catalyst responsible for the metabolism of cholesterol-rich LDL particles." (PMID 25114914, 2014). "As this patient did not demonstrate the metabolic syndrome, greater insulin sensitivity might have led to the rapid decrease in glucose." (PMID 23424590, 2013). "T1DM dyslipidemia may predispose to precocious cardiovascular disease and the lipid status in T1DM under intensive insulin treatment has not been sufficiently explored." (PMID 23398881, 2013). "By beneficially altering cytokine production and macrophage recruitment, the composition of intestinal microbiota and intestinal integrity, LPS- and adipose-induced systemic inflammation, and insulin signaling, DHA may be a useful tool in the prevention of metabolic syndrome." (PMID 23966110, 2013). "Nieves and colleagues reported in insulin resistant, non-obese individuals, that the presentation of dyslipidemia could be explained by differing levels of visceral fat accumulation." (PMID 23855321, 2013). "Individuals considered metabolically healthy but obese (MHO) have high levels of insulin sensitivity but may not display symptoms of hypertension, dyslipidemia, or chronic inflammation." (PMID 23675368, 2013). "We conclude that by beneficially altering cytokine production and macrophage recruitment, the composition of intestinal microbiota and intestinal integrity, lipopolysaccharide- and adipose-induced inflammation, and insulin signaling, DHA may be a key tool in the prevention of metabolic syndrome." (PMID 23966110, 2013). "The metabolic syndrome is defined as a cluster of abdominal obesity, atherogenic dyslipidemia (hypertriglyceridemia, hypo-HDL cholesterolemia, both foster plaque buildup in arterial walls), hypertension, and hyperglycemia (the body cannot properly use insulin or blood sugar)." (PMID 22998770, 2012). "Herein we investigate the effects of whole grain and low insulin response grain products, fatty fish, and bilberries on glucose metabolism and plasma lipidomic profile in individuals with the impaired fasting glucose (IFG) or impaired glucose tolerance (IGT) and features of metabolic syndrome." (PMID 21901116, 2011). "Children with metabolic syndrome had significantly higher levels of waist circumference, BMI, triglycerides, systolic blood pressure, diastolic blood pressure, Insulin, and HOMA-IR than children without metabolic syndrome, but the levels of HDL-C had the reverse results." (PMID 21176200, 2010). "Subjects with metabolic syndrome who took 100 mg RIAA and 500 mg PAC three times daily and followed the AHA Step 1 low-fat diet for 12 weeks experienced significant decreases in fasting TG and insulin levels compared to individuals who took placebo and followed the same diet." (PMID 20721358, 2010).
metabolic syndrome (continued). "A health care provider has two alternative sets of metabolic syndrome definitions whether he or she decides to diagnose patients as having or not having the metabolic syndrome: a definition that require an insulin assay and a definition that do not require it." (PMID 18088443, 2007). "WHO-defined subjects were more insulin resistant than subjects without the metabolic syndrome (mean and SD for log HOMA-IR, 0.53 ± 0.14 vs. 0.07 ± 0.23, respectively, p < 0.05) and had higher Framingham risk scores (mean and SD, 2.99 ± 4.64% vs. 1.10 ± 1.87%, respectively, p < 0.05)." (PMID 18088443, 2007). "Definitions of the metabolic syndrome that also include a measure of central obesity have been developed between 1999 and 2001 by the World Health Organization, The European Group for the Study of Insulin Resistance and the National Cholesterol Education Program (NCEP)." (PMID 17101046, 2006). "Moreover, CRP levels correlate with other components of the metabolic syndrome that are not easily measured in clinical practice, including fasting insulin, microalbuminuria, and impaired fibrinolysis." (PMID 17140429, 2006). "The importance of central obesity is well-recognized in the definitions of metabolic syndrome per the American College of Endocrinology, National Cholesterol Education Program Adult Treatment Panel (ATP III), European Group for the Study of Insulin Resistance, and World Health Organization (WHO)." (PMID 15530168, 2004). "However, once the critical VAT threshold (CVATT) is achieved and metabolic syndrome has begun to develop, then VAT may influence central SCAT to become more VAT-like, i.e., more lipolytic and less sensitive to insulin's adipogenic or lipid storing effects." (PMID 15530168, 2004). "Furthermore, a ‘prudent’ DP was negatively associated with WC, TAG, insulin and frequency of the metabolic syndrome and positively associated with QUICKI (insulin sensitivity) in young US adults, with a lack of relationship for TC, LDL-C, HDL-C, blood pressure, glucose and HOMA-IR." (PMID 40634995, 2025). "Therefore, the positive relationship of high blood adiponectin level with increased risk of AD dementia or higher brain Aβ deposition cannot not be explained by the direct insulin-sensitizing, anti-diabetic, or anti-metabolic-syndrome properties of adiponectin." (PMID 37191420, 2023). "However, oral supplementation of butyrate did not improve insulin sensitivity in obese metabolic syndrome subjects, whereas oral propionate could improve insulin resistance in these subjects." (PMID 35050187, 2022). "However, in metabolic syndrome volunteers, both men and women, the consumption of grape seed along with a meal (670 kcal, 30% fat) reduced the postprandial glucose response, but not that of insulin." (PMID 36615813, 2022). "Despite the developing knowledge in understanding the role of insulin pathways in dyslipidemia, to date no study has considered whether this mechanism works the same in all participants; and whether minor alleles are more likely to be risk alleles in IR mechanisms in metabolic diseases or not." (PMID 34001235, 2021). "Furthermore, low phosphate was suggested to be related with hypertension, reduced insulin sensitivity, and metabolic syndrome, which might help, although not directly, explain the relationship." (PMID 33935953, 2021). "The hypothesis of a role of anatomical contiguity between mouth and gut in influencing this picture is reinforced by the lack of difference in insulin levels between obese with and without periodontal disease, according to previous data in carriers of metabolic syndrome." (PMID 30451975, 2019). "Furthermore, our present results indicated that starting the treatment after the development of metabolic syndrome could not restore glucose tolerance and hence insulin secretion." (PMID 31673100, 2019).
metabolic syndrome (continued). "Patient A did not demonstrate any features of the metabolic syndrome in contrast to patient B. The blood glucose increased rapidly in both patients within 30 minutes; in patient A, it stopped increasing at that point, while in the insulin resistant patient B, it continued to rise." (PMID 23424590, 2013). "The co-existence of metabolic syndrome and SDB/OSA based on visceral fat accumulation, i.e. "Syndrome Z", may represent two sides of the same coin, given the common pathophysiological processes evident in both conditions, such as insulin resistance and atherosclerosis." (PMID 22381117, 2012). "The serum insulin, HOMA-IR levelssignificantly higher in metabolic syndrome patients with hypothyroidism when compared to without hypothyroidism and controls." (PMID 40255297, 2025). "A human pilot study demonstrated that oral butyrate supplementation positively influences glucose metabolism in lean individuals but not in those with metabolic syndrome, likely due to altered SCFA handling in insulin-resistant subjects." (PMID 41007736, 2025). "Exposure to 4mo HFD significantly increased concentration of insulin, leptin and cholesterol but not triglycerides (TAG) or free fatty acids (FFA), which is consistent with the development of the metabolic syndrome." (PMID 38177913, 2024). "Higher levels of FBS, fasting insulin, HOMA-IR, and dyslipidemia were found in obese people with and without T2DM compared to the control group (p < 0.05)." (PMID 39138505, 2024). "Dyslipidemia did not develop until 6 months after STZ-NA treatment and plasma insulin rose progressively over 6 months." (PMID 37730757, 2023). "Although not first-line for dyslipidemia treatment, metformin can also improve dyslipidemia in patients with T2DM through mechanisms that increase insulin sensitivity to reducing LDL and TG." (PMID 36615885, 2023). "However, although metformin reduces serum insulin and may have chemoprevention properties, in our small study we found no impact of the addition of metformin to ADT therapy on risk of metabolic syndrome associated with castration therapy and no additional anti-tumor effects." (PMID 37335291, 2023). "In subjects with metabolic syndrome, most of the parameters (waist circumference, waist-height ratio, FBS, fasting insulin, TGs, T3, and TSH) were significantly higher (p<0.001) as compared to those without metabolic syndrome." (PMID 37809190, 2023). "Despite the absence of metabolic syndrome (MetS), NWO individuals show a higher risk of metabolic disease than normal-weight individuals on account of their lower insulin sensitivity and higher blood pressure, which is accompanied by a higher concentration of inflammatory markers." (PMID 38136166, 2023). "Another SRMA assessed the effect of pistachio intake in individuals with T2D, prediabetes, and metabolic syndrome (6 RCTs), which showed a significant lowering in fasting glucose and HOMA-IR, but not HbA1c or fasting insulin." (PMID 36839236, 2023). "For instance, our study included the Hyper Insulin, Bilirubin, SHBG-LpA, and ALP Negative clusters, whereas the T2DGGI study included clusters labeled as Body fat, Metabolic syndrome, and Residual glycemic." (PMID 37886436, 2023). "Notably, individuals with coexistence of T2DM and metabolic syndrome exhibited a reduction of 59% in insulin-mediated myocardial glucose metabolism than subjects with T2DM without MetS and a reduction of 68% as compared with control subjects." (PMID 35845046, 2022). "The Dreams study aimed to study the impact of RDN in patients with metabolic syndrome and concluded that RDN did not lead to a significant improvement of insulin sensitivity." (PMID 35330342, 2022). "PCOS women with dyslipidemia had increased age, BMI, WC, HC, SBP, DBP, duration of infertility, insulin, HOMA-IR, lower LH, FSH, LH/FSH ratio and SHBG compared to women without dyslipidemia." (PMID 34977197, 2021).
metabolic syndrome (continued). "Compared with participants without metabolic syndrome, those with metabolic syndrome were older and had higher values for urinary ACR, eGFR, BMI, WC, SBP, DBP, TG, FPG, fasting insulin, γ-GGT, and HOMA-IR as well as a lower HDL-C level (all P<0.001)." (PMID 33686966, 2021). "In contrast, no beneficial effect was observed on insulin sensitivity following 6 months DASH dietary pattern intervention, in both individuals with and without metabolic syndrome." (PMID 34136166, 2021). "Another study found that the 72.4% of non-Hispanic women with PCOS had dyslipidemia and elevation in LDL-C was most frequent, and the significant predictors were age, insulin, and testosterone." (PMID 34977197, 2021). "In patients with metabolic syndrome, FMT from metabolic syndrome donors temporarily decreased insulin sensitivity, whereas after FMT from healthy donors, insulin sensitivity was not altered." (PMID 34650994, 2021). "In a primate model of metabolic syndrome, GW501516, an agonist of PPARβ/δ, dose-dependently lowers plasma insulin levels without side effects on glycemic control." (PMID 32708786, 2020). "However, when beta cells in the pancreas are not able to maintain insulin hypersecretion, and it begins to deteriorate, the failure of insulin release is the point of diagnosis in most cases of Metabolic Syndrome (MetS) and T2D." (PMID 31231489, 2019). "This increase in hepatic glucose output occurs independent of any interaction with insulin, glucagon or free fatty acids (FFA).Transgenic mice over expressing 11βHSD1 develop metabolic syndrome but not obesity." (PMID 30678666, 2019). "On the contrary, daily consumption of 30 g of walnuts, almonds, and hazelnuts for 12 weeks resulted in decreased insulin levels with no change in glucose, LDL-C, HDL-C, and TGs in individuals with metabolic syndrome." (PMID 31261928, 2019). "Both increased TGs and decreased HDL-C levels are the characteristics of dyslipidemia, found in insulin-resistant subjects, while the low HDL-C and high TGs level are the hallmarks of atherogenic dyslipidemia both in diabetic and non-diabetic populations." (PMID 29018475, 2017). "Similarly, replacement of SFA with MUFA or a low fat high complex carbohydrate (LFHCC) diets did not improve insulin sensitivity in individuals with the Metabolic Syndrome (MetS), although the incidence of the MetS was reduced." (PMID 27128935, 2016). "However the lack of other significant biochemical differences in the markers of ED suggests that higher non-fasting insulin, which is indicative of a reduced insulin sensitivity and carbohydrate tolerance, may precede the development of ED and other features of the metabolic syndrome." (PMID 26196519, 2015). "In a primate model of the metabolic syndrome, the PPAR-β/-δ selective agonist GW501516 dose-dependently lowered plasma insulin levels, without adverse effects on glycemic control." (PMID 23781121, 2013). "Conversely, there was no improvement in insulin sensitivity and HDL, which are other parameters of the metabolic syndrome." (PMID 22848584, 2012). "Obese with metabolic syndrome group had higher CRP and insulin level in comparison with obese without metabolic syndrome group." (PMID 22691465, 2012). "Both HIV+ and HIV-negative men with ATP-III metabolic syndrome had significantly lower GLUT/INS than HIV-negative men without the metabolic syndrome, and both tended to be lower than HIV+ men without the metabolic syndrome (data not shown)." (PMID 22151886, 2011). "The lack of a significant difference in insulin sensitivity could also be explained by the fact that our comparison group was morbidly obese children with metabolic syndrome rather than a control group of obese subjects without metabolic syndrome or lean, healthy control subjects." (PMID 18762497, 2008).